HMGB1 (high mobility group box 1)
Diseases named in the same sentence as HMGB1 in open-access papers (continued):
Sharing a sentence is not in itself a finding about the gene and the disease.
tumor (continued). "HMGB1 can accelerate the generation of pro-tumor inflammation via NF-κB and inflammasome pathways; however, the current study suggests that it plays a dual role in tumor immunity." (PMID 35372083, 2022). "The Western blotting results of tumour tissues displayed the lowest expression of HMGB1 protein in the miR-495-3p lentivirus group and the highest in the HMGB1 lentivirus group." (PMID 35354479, 2022). "Recent studies reported that some DAMPs such as HMGB1 and ATP accelerate tumor progression and contribute to resistance to anti-cancer therapies." (PMID 36145510, 2022). "This study analysed the genetic changes, RNA expression, protein expression and DNA methylation of HMGB1 in more than 30 tumours." (PMID 35765707, 2022). "In brief, our research group presents multicancer analysis of HMGB1 combined with the study of clinical survival prognosis, methylated DNA, phosphorylated proteins, tumor-infiltrating immune cells, TMB, and MSI in different tumors." (PMID 36230798, 2022). "In this study, we also found that patients with high expression of HMGB1 had larger tumor volume and later TNM stage." (PMID 36260180, 2022). "In brief, we first neutralized the secretion of HMGB1 from tumor cells by a direct HMGB1 antagonist, glycyrrhizin (GL)." (PMID 34617194, 2022). "Since the progression of cSCC is correlated with HMGB1 overexpression, it is plausible to suppose that high levels of HO-1 can contribute to stem neoplasia growth and metastasis." (PMID 35207500, 2022). "The involvement of HMGB1 is complex in many cancers, e.g., nuclear or extracellular HMGB1 is engaged in tumor formation, progression, metastasis, and even in the response to chemotherapeutics." (PMID 36230798, 2022). "In established tumors, conflicting roles have been described for HMGB1, including the activation of tumor-promoting inflammatory responses and immunosuppressive pathways, as well as the induction of anti-tumor responses." (PMID 36032129, 2022). "The present results indicated that extracellular HMGB1 exerted tumor progressive effects that were attenuated by rTM, resulting in the inhibition of tumor growth." (PMID 35328684, 2022). "On the one hand, massive release of HMGB1 and ATP or cytokines/chemokines during necroptosis could enhance the pro-inflammatory effect and induce attraction of myeloid-derived suppressor cells and/or tumor-associated macrophages, which eventually leads to tumor-associated immune suppression." (PMID 35562364, 2022). "In established tumors, HMGB1 released by tumor cells can exacerbate inflammation to promote tumor growth." (PMID 35927755, 2022). "HMGB1 acts as a key regulator in the crosstalk between GB cells and tumor-suppressive M1-like TAMs in GB microenvironment and enhances TMZ sensitivity of GB cells." (PMID 35193644, 2022). "Regarding ESCC, it has been reported that HMGB1 was overexpressed in the tumor and plasma of ESCC patients, and high levels of HMGB1 in ESCC tissues were associated with tumor progression, poor prognosis, and development of radioresistance." (PMID 34617194, 2022). "These B cells were enriched in tumor nests with high expression of high-mobility group box 1 (HMGB1)." (PMID 34617194, 2022). "Considerable emphasis has been paid to the proinflammatory role of secreted HMGB1, while other reports also link HMGB1 cellular distribution with the promotion of tumor cell metabolism." (PMID 36047643, 2022). "Together, our data show that both forms of HMGB1 can act on tumor cell fate by inducing either a cytotoxic or a cytostatic effect." (PMID 35887213, 2022). "The administration of rTM decreased inflammatory cytokines and inhibited angiogenesis via the suppression of HMGB1 in non-tumor diseases in gynecology." (PMID 35328684, 2022).
tumor (continued). "Compared with tumors in mice injected with EC18H tumor cells alone, higher tumor growth rate was observed in mice injected with B cells mixed with HMGB1-overexpressing tumor cells (labeled as EC18H/B in red)." (PMID 34617194, 2022). "We observed that the proliferation rate of B cells co-cultured with HMGB1-overexpressing tumor cells was higher than that of their vector control cells." (PMID 34617194, 2022). "Collectively, our results suggest that B cells within the TME, being primed by HMGB1 released from cancer cells, migrate to the tumor." (PMID 34617194, 2022). "HMGB1 also plays a protective role in tumor suppression and immunotherapy by regulating DNA damage repair and inducing the Th1 response." (PMID 35493517, 2022). "The core regulatory mechanism describes the release of CALR, ATP, and HMGB1 molecules from dying tumor cells, and inner-state activation or evolution of immature DC, activated DC, migrating DC, lymph node DC, T cell, and cytotoxic T lymphocyte cell types." (PMID 37420422, 2022). "On the one hand, IRE induced tumor cell necrosis and release of DAMPs including adenosine triphosphate (ATP), high mobility group box 1 (HMGB1) and calreticulin to stimulate anti-tumor immunity." (PMID 36505437, 2022). "HMGB1 activates the TLR4/MyD88 signaling pathway in DCs and thus efficiently processes antigens associated with the presentation of dying tumor cells." (PMID 35637945, 2022). "Re-expression of HMGB1 by stable transfection of the HMGB1 gene in the knockout clones enhanced the in vivo tumor growth." (PMID 35150340, 2022). "Chemotherapy can trigger immunogenic tumor cell death, which results in releasing of stimulatory factors, such as apoptotic tumor cells, ATP and high-mobility-group box 1 (HMGB1)." (PMID 36244976, 2022). "A surrogate biomarker of ICD is the release of HMGB1 from dying tumor cells, which is required for the processing and cross-presentation of antigens and for the recruitment of T cells to the tumor microenvironment (TME)." (PMID 36430552, 2022). "The single exception was arginase 1 (Arg-1), a marker of myeloid-derived suppressor cells (MDSCs), which was expressed more highly in the HMGB1-knockout tumor tissues than the WT tumor tissues." (PMID 35150340, 2022). "Then, SEMA3B-AS1 can promote the transcription and expression of FBXW7 through binding HMGB1, thus promoting autophagy and inhibiting apoptosis in tumor cells." (PMID 35273678, 2022). "S. mitis also down-regulated the inflammatory pathways JAK/Stat, HMGB1 and acute phase response, which are known to be involved in tumor progression." (PMID 35600164, 2022). "Tumor-derived exosomal HMGB1 can expand regulatory B cells by upregulating TIM-1 and thereby promote the immune escape of HCC cells." (PMID 35126514, 2022). "Further, HMGB1 released from the tumor cells promotes antigen cross-presentation of DCs via the activation of TLR4-MyD88." (PMID 36139006, 2022). "To validate these results, we investigated the angiogenic components in the CM after co-culture with HMGB1-overexpressing tumor cells, using human angiogenesis arrays." (PMID 34617194, 2022). "Strikingly, by Kaplan–Meier analysis, the OS of cases that were highly positive for both proliferating B cells and HMGB1-expressing tumor cells was shorter than for those with low expression of both factors (p = 0.045)." (PMID 34617194, 2022). "In the present study, high expression levels of HMGB1 in tumor tissue correlated with high plasma HMGB1 concentrations, which is consistent with previous findings." (PMID 35328684, 2022). "RAGE and HMGB1 interaction can induce the activation of cell signaling pathways including NF-kB, p38, p44/42 MAPKs involved in the tumor progression and metastasis." (PMID 35829833, 2022). "The ecto-CRT is a phagocytic signal recognized by CD91 that promotes antigen presentation of tumor neoantigens in presence of HMGB1 activation." (PMID 36439184, 2022).
tumor (continued). "Zhang pointed out that HMGB1 is enriched in gastric cancer-derived exosomes and can induce neutrophil autophagy and activate tumor-promoting effects." (PMID 35126514, 2022). "Reports also suggest Amphotericin B (AmB) enhances the anti-tumor immune response by releasing HMGB1, which induces ICD." (PMID 36248807, 2022). "Besides, some of the immune-related factors associated with tumor invasion and metastasis such as HMGB1 and Toll-like receptor 4 (TLR4) play a considerable role in rebuilding TIM and promoting the development of pyroptosis that could also be upregulated by hypoxia." (PMID 36204682, 2022). "Through the activation of EMT, high mobility group box protein 1 (HMGB1) derived from NETs enhanced tumor extravasation during metastasis in a murine model of liver metastasis." (PMID 36060811, 2022). "HMGB1-dependent dsDNA uptake and cytosolic transfer appears to be particularly important in the context of tumors where necrotic tumor cells shed dsDNA which is taken up in the form of HMGB1-dsDNA complexes." (PMID 35911757, 2022). "Intracellular HMGB1 is released extracellularly from immune cells during inflammation or from tumor cells due to cytotoxicity, stress, necrosis, and autophagy." (PMID 35328684, 2022). "In mice, HMGB1 released from chemotherapy-induced necrotic tumor cells induced NK cell activation and infiltration into the tumor." (PMID 36032129, 2022). "An alternate innate tumor sensing pathway involves the high-mobility-group box 1 (HMGB1) alarmin protein." (PMID 35626062, 2022). "The combination of cyclophosphamide and oxaliplatin in NSCLC patients significantly increased nuclear HMGB1 staining in tumor nodules; Also, the oxaliplatin cyclophosphamide combination was able to control tumor growth." (PMID 36003765, 2022). "The continuous ICD in the tumor by DP-NPs 6.27 to 9.39-fold higher HMGB1 release than that of PBS-treated tumor tissues led to higher DC maturation and elicited a higher proportion of CTLs into tumor tissues." (PMID 35335852, 2022). "Albeit, it has previously been suggested that HMGB1 plays a multifaceted role in tumor progress or therapy." (PMID 35093187, 2022). "Previous studies have shown that HMGB1 protein is involved in various tumor development processes, especially for proliferation and invasion." (PMID 36260180, 2022). "The levels of HMGB1 phosphorylation in normal and primary tumor tissues were analyzed for BRCA, clear cell RCC, LUAD, and UCEC via the CPTAC web server." (PMID 36230798, 2022). "Together, our data highlight the relevance of tumor cell-derived HMGB1 in inducing proangiogenic B-cells activities." (PMID 34617194, 2022). "HMGB1 is a highly conserved nuclear protein expressed in a variety of cells, and abnormally high HMGB1 expression can be found in lymphoid tissue, thymus, and tumor tissue." (PMID 36544080, 2022). "HMGB1 is secreted by cancer cells and promotes tumor growth, invasion and metastasis by binding to a variety of cell surface receptors (including receptors for advanced glycation end products (RAGE) and Toll-like receptors)." (PMID 36081910, 2022). "WB and immunofluorescence assay on the extracted 4T1-luc tumor tissue samples showed evidently increasing levels of typical DAMPs including HMGB1 and CRT, evidencing the successful ICD induction in vivo." (PMID 36167857, 2022). "We found that apoptotic tumor cells induced by ORFV NA1/11 infection increased the relative protein levels of cytoplasmic HMGB1 in A549 and LLC cells." (PMID 35959371, 2022). "The local chemotherapy Rg3-PNPs + DOX@PPP augmented the ICD effect in mice, via CRT translocation and HMGB1 release, which further stimulated DC maturation to phagocytize dead tumor cells, and to present antigens." (PMID 36494759, 2022). "CLSM results show that the MH + US and MHS + US group markedly promoted the outflow of the HMGB1 protein from tumor cells." (PMID 36550159, 2022).
tumor (continued). "Intracellular HMGB1 regulates DNA repair systems and autophagy in tumor cells to induce radioresistance." (PMID 35812184, 2022). "qRT-PCR analysis of genes implicated in angiogenesis process demonstrated that angiogenic factors, VEGF, IL8, TGFβ, and MMP9 were increased in the B cells co-cultured with HMGB1-overexpressing tumor cells as compared to control cells." (PMID 34617194, 2022). "Previous studies have revealed that HMGB1 creates an inflammatory tumor microenvironment between EAC cells and macrophages, which further promotes the progression of EAC." (PMID 36553511, 2022). "Quantification of VEGF and Ki67 expression by FACS in B cells confirmed the increased frequencies of proliferating VEGF+ B cells upon co-culture with HMGB1-overexpressing tumor cells." (PMID 34617194, 2022). "A key characteristic of ICD is the release of danger-associated molecular patterns (DAMPs) by tumor cells, which include ATP, calreticulin (CALR), and high mobility group box 1 (HMGB1)." (PMID 35979349, 2022). "Recently, HMGB1 was reported to be over‐expressed in a number of cancers and involved in tumour invasion and metastasis." (PMID 33191617, 2021). "Tumor HMGB1 and TLR4/RAGE receptors promote cell proliferation, survival, migration, epithelial-to-mesenchymal transition, and apoptosis resistance involving interaction with β-catenin, Runx2, YAP1, and TGF-β1/Smad." (PMID 33669632, 2021). "Overall, the analysis of tumor volume in different groups showed that exogenous HMGB1 promotes residual tumor proliferation in vivo." (PMID 34805222, 2021). "During activation of anti-tumour immunity and pro-inflammatory microenvironment, Toll-like receptors play a significant role by binding to a molecule such as HMGB1 (high-mobility group box protein 1)." (PMID 34281259, 2021). "To confirm the involvement of tumor-secreted HMGB1 in macrophage polarization, we carried out the same co-culture experiment, this time supplemented with HMGB1 neutralizing antibody." (PMID 34207850, 2021). "In this work, it was observed that HMGB1 was dramatically raised in PTC tumor tissues and cell lines, and HMGB1 mRNA expression was negatively correlated with miR-1179 expression and positively correlated with circ_0062389 expression in PTC tumor tissues." (PMID 33926347, 2021). "HMGB1 has been reported as a ligand for TIM-3 expressed by tumor-infiltrating DCs, and it has recently been suggested that the binding of HMGB1 to TIM-3 on regulatory CD8+ T cells can inhibit the expansion of effector T cells." (PMID 34572417, 2021). "Nevertheless, during tumor development and cancer therapy, HMGB1 has been reported to play paradoxical roles in promoting both cell survival and death by regulating multiple signaling pathways." (PMID 34465721, 2021). "Taken together, these results indicate that exosomal HMGB1 secretion from tumor cells promotes the formation of an immunosuppressive microenvironment and reduces antitumor responses." (PMID 34599143, 2021). "HMGB1 is also overexpressed in tumor xenografts allowing tumor cells to resist apoptosis in the presence of chemotherapies." (PMID 33567616, 2021). "We and others have shown that HMGB1 is an important mediator of DC activation and promotion of anti-tumor immunity." (PMID 34187428, 2021). "HMGB1 has been demonstrated a tumor-promoting protein and involved in many aspects of tumor progression including proliferation, invasion, metastasis and drug resistance." (PMID 33747917, 2021). "Abundant macrophages infiltrated tumor tissue in the cases with higher HMGB1 expression, whereas few infiltrating macrophages were present in cases with weak HMGB1 expression." (PMID 34244567, 2021). "Based on genomic datasets, the expression profiles of candidate genes in CCA cases were analyzed using GEO databases and the increasing levels of feasible tumor markers including HMGB1, SOX9, and YAP1 in patients with CCA." (PMID 35201494, 2021).
tumor (continued). "Cytoplasmic HMGB1 plays a role in tumor progression by promoting autophagy and activating the inflammasome." (PMID 34360919, 2021). "As one of the DAMPs that significantly enhance the anti-tumor immune effect after radiation, the exposure level of HMGB1 is of great significance for the immune surveillance of the tumor microenvironment." (PMID 33968889, 2021). "We first analyzed the mRNA expression levels of damage-associated molecules (HMGB1, HSP60, HSP70, S100A8, IL-1A, IL-33) in 11 canine tumor cell lines." (PMID 33875721, 2021). "For instance, it has been shown that the alarmin high mobility group protein B1 (HMGB1) recruits nucleic acids from dead tumor cells into DCs endosomes, leading to the innate sensing of tumors." (PMID 34078376, 2021). "Along with the receptor for advanced glycation end products, HMGB1 was described to enhance mitochondrial ATP production in malignant cells contributing to tumor progression." (PMID 34302528, 2021). "The release of HMGB1 by irradiated tumor cells, that we have detected especially with 3 × 8 Gy, was however shown to promote proliferation of living tumor cells." (PMID 33572437, 2021). "In this study, we investigated the role of exogenous HMGB1 in tumor proliferation and metastasis using human SW1990 and PANC-1 cells after radiotherapy." (PMID 34805222, 2021). "Several marker genes, FOXP3, STAT3, PDCD1, TGFB1, IL10, HMGB1, which are significantly related to the tumor microenvironment induced by radiation, had significant functional differences in the distribution of CD8+T cells clusters." (PMID 33968889, 2021). "Many of these proteins interact with HMGB1 and HMGB2 whose overexpression is linked to tumor progression, metastasis and poor prognosis." (PMID 34680291, 2021). "HMGB1 is highly abundant in eukaryotes, where high expression has been reported in many tumor types including bladder cancer." (PMID 33986291, 2021). "Exosome-mediated transfer of high mobility group box-1 (HMGB1) from GC cells activates neutrophils by NF-κB pathway, which promotes tumor cell’s migration." (PMID 34268118, 2021). "That is, the in vivo tumor growth was accompanied by increased platelet activation, exosome release, exosomal HMGB1, and tumor platelet infiltration, and dipyridamole and GW4869 displayed ameliorating effects." (PMID 33669632, 2021). "Besides, another research demonstrated that exosomal High Mobility Group Box 1 (HMGB1) obtained from ESCC could successfully trigger clonal expansion of PD1 positive tumor-associated macrophages (TAMs), which thereby created conditions for the development of ESCC." (PMID 34527593, 2021). "Our results showed that HMGB1 was expressed at higher levels in GC tissues and cells compared with adjacent non-tumour tissues and normal gastric epithelial cells, respectively." (PMID 33391448, 2021). "HMGB1 promotes development and metastasis of prostate cancer and colorectal cancer; on contrary, it acts as tumor suppressor in pancreatic cancer and endometrial carcinoma." (PMID 34552063, 2021). "This study reveals for the first time the role of HMGB1 in neosis‐based tumor repopulation, consolidating and enriching the role of HMGB1 in tumor recurrence after therapy and tumor progression." (PMID 33523579, 2021). "Recent studies further demonstrated that pyroptosis of tumor cells and the release of HMGB1 are able to induce effective antitumor immunity." (PMID 34630087, 2021). "RAGE binds to a range of damage-associated molecular pattern molecules (DAMPs) including AGEs, HMGB1, S100s, and DNA which mediate downstream cellular responses that promote tumor growth, angiogenesis, and invasion." (PMID 34975408, 2021). "High-mobility group box1 (HMGB1) released from tumor cells is an endogenous ligand of platelet toll-like receptor 4 (TLR4)." (PMID 34722319, 2021). "In vitro, the protein HMGB1 promotes NET formation through a TLR4-dependent manner and in vivo, inhibition of both HMGB1 and NETs significantly delays tumor growth." (PMID 33986291, 2021).